LEP (leptin)
Diseases named in the same sentence as LEP in open-access papers (continued):
Sharing a sentence is not in itself a finding about the gene and the disease.
metabolic syndrome (continued). "Therefore, this study aims to assess the effects of PM2.5 exposure on metabolic and hormonal parameters, specifically insulin, adiponectin, leptin, and HOMA-IR, by comparing healthy individuals and individuals with metabolic syndrome across two distinct PM2.5 seasons in Chiang Mai, Thailand." (PMID 40863890, 2025). "Meanwhile, LEP expression was not correlated with dyslipidemia." (PMID 36157437, 2022). "Novel clinical (adiponectin, leptin, and adiponectin-to-leptin ratio), molecular, and omic biomarkers have been inventoried within HBM4EU and proposed as biological indicators that could help to identify the role of PFAS in metabolic syndrome." (PMID 36006128, 2022). "However, our previous study found that bipolar patients who received valproate had increased peripheral leptin levels, and VPA has been confirmed to stimulate appetite and decrease thermogenesis in the hypothalamus, resulting in weight gain and metabolic syndrome." (PMID 36077028, 2022). "The leptin to adiponectin ratio (LAR), which has an inversely proportional relationship with adiponectin to leptin ratio, has been shown to correlate with carotid intima-media thickness as well as insulin sensitivity and to predict the presence of the metabolic syndrome." (PMID 34977280, 2022). "Subjects with metabolic syndrome had higher leptin levels than those without metabolic syndrome." (PMID 34769215, 2021). "In men, the leptin/ghrelin ratio had a better capacity to identify patients with metabolic syndrome (AUROC = 0.923, Se = 76.9%, Sp = 100%) compared to leptin (AUROC = 0.821), ghrelin (AUROC = 0.718), or the HOMA index (AUROC = 0.654); p = 0.09 between the leptin/ghrelin ratio AUROC vs. AUROC-HOMA." (PMID 34829886, 2021). "Furthermore, SS patients with metabolic syndrome have increased serum levels of leptin and interleukin (IL)-1β compared to those without metabolic syndrome." (PMID 32370746, 2020). "Also, the authors found that LAR has better capacity in the classification of subjects with and without metabolic syndrome than adiponectin or leptin alone." (PMID 28878827, 2017). "Furthermore, components of the metabolic syndrome were correlated positively with leptin/HMW adiponectin ratio, independent of parameters including age, smoking status, exercise, low-density lipoprotein (LDL) cholesterol, and BMI." (PMID 25650072, 2015). "Taken together, our data suggest that maternal HFD during lactation might have an additive effect on the onset of the metabolic syndrome-like phenomenon in the offspring irrespective of the nutritional status in utero through the modified leptin surge." (PMID 24664181, 2014). "Our data suggested that maternal HFD during lactation might have an additive effect on the onset of the metabolic syndrome in the offspring, irrespective of the nutritional status in utero through the modified leptin surge." (PMID 24664181, 2014). "The results of the present study showed that neither soy protein, nor soy nut could affect weight and serum leptin levels in postmenopausal women with metabolic syndrome." (PMID 21526104, 2010). "The results of the present study on a group of postmenopausal women with the metabolic syndrome indicated that neither soy protein nor soy nut could change the serum leptin levels." (PMID 21526104, 2010). "Leptin levels were higher and adiponectin levels were lower in AA men and women than in their NHW counterparts, which may contribute to glucose intolerance and metabolic syndrome in AA individuals." (PMID 20140090, 2010). "Consequently, treatments that reduce leptin levels, like metformin, thioazolinediones, pioglitazone and statins, which are used to treat metabolic syndrome and insulin resistance, have also demonstrated benefits in downregulating inflammation in EAE and in pwMS with metabolic syndrome." (PMID 39599673, 2024).
metabolic syndrome (continued). "Moreover, in a rat model of metabolic syndrome (MetS), PRAT-derived leptin exacerbates the proliferation of glomerular endothelial cells by activating the MAPK pathway." (PMID 34408726, 2021). "However, further elevation in the leptin-resistant state will not improve metabolic syndrome." (PMID 31718027, 2019). "Subjects in the highest tertile of leptin, PAI-1 and hsCRP had higher odds of having Metabolic Syndrome (MetS) (odd ratio [OR] = 3.02, 95% confidence interval [CI] = 1.47 – 6.19) and (OR = 2.52, 95% CI = 1.45 – 4.35), (OR = 4.26, 95% CI = 2.39 – 7.59) respectively." (PMID 24716628, 2014). "Although the results of previous studies indicated beneficial effects of soy consumption on the cardio-metabolic abnormalities, the results of the present study showed that neither soy protein nor soy nut could effect weight or serum leptin levels in postmenopausal women with metabolic syndrome." (PMID 21526104, 2010). "Results show that serum leptin and TSH aresignificantly correlated among metabolic syndrome patients with and without hypothyroidism." (PMID 40255297, 2025). "Exposure to 4mo HFD significantly increased concentration of insulin, leptin and cholesterol but not triglycerides (TAG) or free fatty acids (FFA), which is consistent with the development of the metabolic syndrome." (PMID 38177913, 2024). "However, another study showed increased leptin levels in metabolic syndrome as well as patients with spondyloarthritis but not in patients with RA after one year of treatment with DMARD, and a decrease in disease activity correlated with decreased leptin levels could be observed in this study." (PMID 33499006, 2021). "The three included case-control studies were not specific to leptin levels (NHS: type 2 diabetes and breast cancer; GEMS: dyslipidemia; Health 2000: the condition for cases not mentioned)." (PMID 34594363, 2021). "A study conducted on urban South African blacks with and without coronary artery disease (CAD) revealed that leptin differentiated between CAD patients with and without metabolic syndrome and determined metabolic syndrome status in women and men." (PMID 27189377, 2016). "With respect to the lipid profile, as an essential component of metabolic syndrome diagnosis, we observed a negative correlation between the ADPN/LEP ratio and the TG/TCH ratio in women." (PMID 26389928, 2015). "The obese participants without metabolic syndrome presented significant reductions in weight, BMI, TC, LDL-C, CRP and leptin, and an increase in HDL-C in response to training." (PMID 22691465, 2012). "The body weight, BMI, waist circumference, systolic and diastolic blood pressure, as well as TC, LDL-C, TG, leptin, and CRP levels were significantly higher in the obese group without metabolic syndrome than in the control group." (PMID 22691465, 2012). "Whereas increased metabolic syndrome incidence was observed in males with elevated leptin regardless of CRP levels, females with elevated CRP or leptin had increased incidence of metabolic syndrome." (PMID 22533665, 2012). "Among the molecular mechanisms explaining the in vivo effect on metabolic syndrome, the effect of PBJ constituents on the regulation of energy homeostasis through leptin networking should also be considered, and since this was not explored in the present paper, it deserves further investigation." (PMID 37049725, 2023). "Serum leptin levels showed significant negative correlations with eGFR levels (β=-0.14, p<0.01) in the multivariate linear regression after adjusting for age, sex, smoking status, drinking status, BMI, uric acid levels, HTN, DM, and dyslipidemia." (PMID 36619557, 2022). "Moreover, systemic treatment of metabolic syndrome animals with dopamine agonist reverses the syndrome and the VMH noradrenergic hyperactivity and appears also to reverse the VMH leptin resistance all without altering food consumption." (PMID 33485386, 2021).
breast cancer (620 papers, 2004 to 2026). A primary or metastatic malignant neoplasm involving the breast. "Leptin, an adipokine secreted by adipose tissue, is implicated in breast cancer development and represents a potential therapeutic target, particularly for obese women with breast cancer." (PMID 40565190, 2025). "Studies indicate that variation in the promoter region of the LEP gene at position − 2548 is linked to elevated breast cancer risk, with this association being more pronounced in women with obesity." (PMID 41269404, 2025). "In breast cancer patients, serum leptin associates with worse clinical features, and is highest in TNBC, compared to HR-positive tumors." (PMID 40034592, 2025). "Specifically, the LEP − 2548AA genotype confers a slightly higher risk of breast cancer compared to the − 2548GG genotype." (PMID 41269404, 2025). "Increased leptin is associated with increased body fat mass and promotes breast cancer cell growth by hindering proapoptotic signaling pathways." (PMID 40713647, 2025). "The WISER Survivor trial in overweight/obese breast cancer survivors observed significant decrements in leptin in the weight loss arms." (PMID 38279016, 2024). "Although the structural distinctions between Upd2 and human leptin are evident, it is noteworthy that human leptin has been implicated in diverse human cancer types, with elevated leptin levels linked to the aggressiveness and prognosis of breast cancer." (PMID 39642218, 2024). "Leptin, derived from fat cells, stimulates the growth of breast epithelial cells and is a risk factor for breast cancer, especially in obese postmenopausal women." (PMID 38553750, 2024). "Studies, such as one involving a high-risk breast cancer population, have demonstrated that aerobic exercise training can reduce breast cancer risk by lowering body fat and modulating levels of leptin and adiponectin." (PMID 39346906, 2024). "A meta-analysis of 35 studies linked higher serum leptin levels with increased breast cancer risk, especially in postmenopausal women, suggesting its potential as a biomarker." (PMID 39251829, 2024). "This review investigates the role of leptin in regulating angiogenesis, specifically within the context of breast cancer and the associated tumor microenvironment in obese patients." (PMID 39439572, 2024). "It has also been found that high leptin levels are associated with an increased risk of colon and breast cancers." (PMID 39410536, 2024). "Upregulation of IL-18 by leptin facilitates the migration and progression of breast cancer cells and is also implicated in metastasis in gastric cancer, melanoma, and tumor growth in colorectal cancer." (PMID 38255203, 2024). "The purpose of this study was to determine the role of leptin-induced autophagy in cancer cell metabolism and its association with cellular proliferation and migration in breast cancer cells." (PMID 38228661, 2024). "Multiple leptin-mediated pathways have been described in breast cancer cells, that have been linked to proliferation, cell migration, and increase in therapeutic resistance." (PMID 38238336, 2024). "Leptin, implicated in inflammatory, mitogenic, and pro-angiogenic pathways, has been associated with breast cancer development, with studies indicating that inhibiting leptin signaling reduces the growth of breast cancer induced by carcinogens." (PMID 38801466, 2024). "For LEP rs7799039, the association was significant in studies with prospective design, with histologically-confirmed breast cancer, and involving sample size exceeding 300 under three genetic modes of inheritance." (PMID 37274250, 2023). "An increased leptin–adiponectin ratio was associated with an increased risk of some types of cancer such as breast cancer, endometrial cancer, colorectal cancer, pancreatic cancer, and prostate cancer." (PMID 37444627, 2023).
breast cancer (continued). "The aim of this meta-analysis was to examine the association of 5 genetic alterations in LEP and ADIPOQ genes, as well as their receptor-encoded genes, with breast cancer risk and circulating leptin levels." (PMID 37274250, 2023). "Even though these proposed mechanisms have been widely accepted, there have been contradicting results regarding leptin’s role in the risk of breast cancer development." (PMID 36900364, 2023). "Our study included breast cancer survivors who were overweight or obese at baseline and observed that weight loss was associated with decreased leptin levels and an increased A:L ratio." (PMID 37571390, 2023). "Since triple-negative subtypes of FMC were shown to have both high tumor and serum expression of leptin, this suggests that leptin is associated with more aggressive and proliferative mammary carcinomas, which was also reported in human breast cancer." (PMID 37626804, 2023). "Higher leptin levels are associated with an increased risk of breast cancer recurrence and worse overall survival in breast cancer patients." (PMID 37571390, 2023). "Other studies have proven that there is an association between leptin levels, estrogen, and progesterone receptor expression in breast cancer patients." (PMID 36900364, 2023). "The decrease in leptin levels represents a favorable modulation because of its association with a lower risk of breast cancer recurrence." (PMID 37571390, 2023). "Recent data revealed that leptin induces expression of Notch family components associated with IL-1 signaling in breast cancer." (PMID 38152619, 2023). "For example, the interaction between leptin and IL-1 in breast cancer cells is linked to the promotion of pro-inflammatory and pro-angiogenic signals, contributing to the progression of breast cancer." (PMID 38202341, 2023). "The association between leptin levels and estrogen status in breast cancer has been previously studied as well." (PMID 36900364, 2023). "Although the serum leptin level has been shown to positively correlate with breast-cancer risk in postmenopausal women, an inverse relationship has been reported in premenopausal women." (PMID 37238961, 2023). "A multiethnic case-control study further demonstrated that a reduced adiponectin/leptin ratio was associated with increased risk of postmenopausal breast cancer, which was also shown in preclinical models." (PMID 37181043, 2023). "Further, increased leptin associates with breast cancer risk at a standardized mean difference of 0.96 in a meta-analysis of 46 studies of over 13,500 women." (PMID 35752704, 2022). "Previous studies have shown that elevated leptin levels are associated with aggressiveness and poor prognosis of breast cancer patients." (PMID 35223490, 2022). "Leptin also exerts proinflammatory effects and can render breast cancer cells less susceptible to treatment with tamoxifen." (PMID 36401194, 2022). "A high expression of leptin (LEP) and low levels of adiponectin in obese patients were identified associated with the occurrence of breast cancer." (PMID 35223490, 2022). "Higher circulating leptin concentrations were significantly associated with an increased risk of breast cancer." (PMID 35223490, 2022). "A previous study has shown that serum leptin levels are positively associated with increased expression of ER and PR in breast cancer patients." (PMID 35223490, 2022). "Serum expression levels of leptin, resistin, and visfatin are reliable diagnostic markers of breast cancer and are independent predictive factors of LN invasion and ER-negative breast cancer patients." (PMID 35701840, 2022). "By itself, leptin appears to be enough to cause breast cancer, which would explain the premenopausal cases." (PMID 36142655, 2022). "WHEL was the only study to assess relationships between selected adipokines and breast cancer events, reporting null associations for both leptin and adiponectin." (PMID 36401194, 2022).
breast cancer (continued). "Elevated levels of leptin were observed in higher grade and advanced tumor stages of breast cancer and were associated with a poorer outcome in triple-negative breast cancer." (PMID 36401194, 2022). "In a recent meta-analysis leptin was demonstrated to be a significant risk factor for breast cancer in overweight/obese post-menopausal women." (PMID 36077676, 2022). "Increased under obese conditions, leptin is associated with increased breast cancer risk and thereby serves as a potential biomarker for post-menopausal overweight/obese patients." (PMID 35186923, 2022). "Increased leptin due to obesity explains the increased risk of invasive/metastatic tumors and overall poor survival in obese breast cancer patients." (PMID 35186923, 2022). "Serum levels of several adipokines, mainly leptin and adiponectin, have been intriguingly associated with an increased risk of breast cancer in multiple studies and meta-analyses." (PMID 36428526, 2022). "A 6-month weight loss intervention in breast cancer survivors who completed chemotherapy and/or radiation therapy led to changes in body weight and fat, serum levels of leptin and adiponectin, and breast tissue levels of CD163." (PMID 35256599, 2022). "Classic adipokines, such as leptin, adiponectin, and resistin, have been extensively studied in breast cancer and connected with breast cancer risk and progression." (PMID 36077676, 2022). "Another growth promoter, associated with increased leptin production, is oestrogen, whose role in breast cancer is well established." (PMID 36038791, 2022). "Several single-nucleotide polymorphisms (SNPs) of LEP and LEPR were found correlated with breast cancer risk, including LEP-2548G/A (rs7799039), LEPR K109R (rs1137100), and LEPR Q223R (rs1137101), but the results are not exactly consistent." (PMID 35223490, 2022). "As In ours, some studies observed a strong attenuation of the associations between CRP and leptin and postmenopausal breast cancer risk after adjustment for BMI suggesting that BMI was a confounder in the inflammation-breast cancer association." (PMID 35430795, 2022). "Conversely, circulating LEP levels increase with increasing BMI and are associated with increased breast cancer risk in some studies." (PMID 35846306, 2022). "Leptin has been suggested as a potential biomarker of breast cancer risk and cancer progression in women, since it has been found to be overexpressed in breast tumors and metastatic lesions." (PMID 36291097, 2022). "The association of estrogen synthesis in adipocytes and leptin increases the risk of developing breast cancer, due to the continuous activation of aromatase." (PMID 36142655, 2022). "Leptin appears to be a key driver in energy homeostasis and breast cancer tumorigenesis, and its expression is associated with AT mass, BMI, and leptin receptor (OB-R)." (PMID 35701840, 2022). "Similar to what we observed for leptin, a borderline positive association with breast cancer risk was observed for small tumors only, which contrasts with the known anti-inflammatory properties of this adipokine." (PMID 35948877, 2022). "Leptin is associated with adiposity and adipocyte size and can signal to activate breast cancer cell proliferation." (PMID 35775614, 2022). "Leptin and leptin/adiponectin ratio were negatively associated with breast cancer risk when adjusting for waist circumference, although associations were attenuated as compared with the univariate model." (PMID 35948877, 2022). "They noted a strong association between breast cancer risk and higher leptin levels in overweight or obese patients." (PMID 36556428, 2022). "In the present work, leptin was inversely associated with breast cancer risk in both univariate and fully adjusted model, however this association lost significance when the univariate model was adjusted for BMI." (PMID 35948877, 2022).